IL22 (interleukin 22)
Diseases named in the same sentence as IL22 in open-access papers (continued):
Sharing a sentence is not in itself a finding about the gene and the disease.
infection (continued). "Th17 cells exert their biological effects via the secretion of IL-17A, IL-17F, IL-6, IL-22 and TNF-α, which signals neutrophils to move towards the site of inflammation and play an infection-fighting role in the early stage of the immune response." (PMID 23403648, 2013). "The alterations of Th22 cells in Anti-IL-22 Ab, IgG control and PBS groups were investigated by flow cytometry, on day 14 post infection." (PMID 23050732, 2012). "WT mice which received Stat1−/− bone marrow responded to infection with a systemic cytokine storm, i.e elevated serum levels of almost all measured cytokines and chemokines (IL6, IL22, TNFα, MCP1, IL10, Rantes, IP10 and MCP3)." (PMID 22719255, 2012). "Rather IL-22 specifically regulates neutrophil migration and thus WNV entry into the CNS after peripheral infection has been established." (PMID 22952908, 2012). "Additionally, the IL-22-regulated lectin regenerating islet-derived III-gamma (RegIII-γ) which can prevent C. rodentium-induced mortality in susceptible mice, was also highly upregulated in both strains during infection, and elevated at baseline in uninfected Muc2−/− mice." (PMID 20485566, 2010). "Using a host with impaired barrier repair (Il22−/− mice), we confirmed that accessory effectors collectively shape infection outcomes without significantly impacting virulence." (PMID 40599135, 2025). "The low correlations were influenced by Asp infection (lime green star) showing distinctly higher levels for IL‐21 and IL‐22 compared to other types of infection, and MRSA infection (red square) showing distinctly higher levels of TNFα as compared to other infection types." (PMID 40031928, 2025). "Secreted IL-13 was detectable in the pediatric group during the acute phase of infection, and IL-22, but not IL-13, levels correlated with age in the pediatric group (IL-22 P = 0.002 and <0.0001)." (PMID 40906527, 2025). "The cytokine, IL-22, also displayed a significant increase in young mice post-infection with no change in adult and aged mice." (PMID 40732672, 2025). "No neutrophil staining was detected in uninfected Il22+/+ and Il22−/− mice, whereas infection resulted in prominent neutrophil infiltration in the submucosa and mucosa." (PMID 41361166, 2025). "Additionally, at 2% Aq, the expression of the digestive-related enzyme carboxypeptidase B was upregulated in the gut, alongside a significant decrease in IL-22 expression, a cytokine usually increased during WSSV infection in shrimp." (PMID 39857423, 2025). "While ILC2s do not expand in CR-infected Il22-/- mice, injection of IL-18 into Il22-/- mice at 2- and 3-days post CR infection triggered ILC2s expansion." (PMID 40591723, 2025). "The FD4 permeability defect observed in Ptpn2∆IEC mice post-mAIECred infection was also reversed after reconstitution of IL-22 but the same effect was not seen in the Ptpn2fl/fl - mAIECred group." (PMID 40955058, 2025). "In our model, neutralisation of IL-13 during early CR infection did not significantly alter clinical disease parameters but resulted in reduced colonic levels of IL-10 and IL-22." (PMID 40591723, 2025). "Additionally, SCFAs protect the gut from infection and inflammation-induced damage through GPR41-mediated promotion of interleukin-22 (IL-22) production by innate lymphoid cells (ILCs)." (PMID 39502877, 2024). "Both the lungs and brain had their cytokine microenvironment modulated by the absence of IL-23 and IL-22, mainly in the third week of infection." (PMID 39635124, 2024). "Notably, quantification of IL-18 release from the ceca of WT and Il22−/− mice revealed severely reduced levels in Il22−/− mice under both PBS-treated and S. Typhimurium-infection conditions." (PMID 39428744, 2024). "As expected, inflammation score (as measured by cell infiltrates and lack of epithelium integrity) and Il-22 levels increased with Tg infection while Zo1 and Occludin levels decreased." (PMID 38950025, 2024).
infection (continued). "In fact, only the experimental animal group without IL-22 cytokine displayed extensive and increasingly fungemia throughout the entire infection course, despite the fungal burden control in the lungs." (PMID 39635124, 2024). "However, the percentage of IL-22+ CD4+ T cells and IL-22+ ILC3 was maintained at an equal level in the water-restricted mice compared to the control group on days 12 post-infection." (PMID 38799550, 2024). "Differently, when the infection is not undergone, non-leukocyte cells, or pneumocytes are the major source of IL-22 in the lung of uninfected animals, a scenario that is absent in the infection in course." (PMID 39635124, 2024). "This suggests that the peak of fungemia, which was possibly linked to fungal barrier evasion in the lungs around 12 dpi, kept uncontrolled throughout the infection in the absence of IL-22." (PMID 39635124, 2024). "Finally, organoid experiments further verified that IL-22 secreted by ILC3 can enhance the intestinal mucosal immune barrier and inhibit STM infection." (PMID 39080852, 2024). "Moreover, the percentages of IL-22+ cells among total ILC3s were significantly increased, and the MFI of IL-22 in ILC3s was greater at 4 h post infection." (PMID 39695888, 2024). "Both resident and recruited populations displayed significant levels of infection (GFP fluorescence), but the resident population displayed a much higher proportion of cells displaying IL-22 production than the much more numerous recruited population (tdTomato fluorescence)." (PMID 38543790, 2024). "The absence of IL-22 in CD4+ T cells results in an inability to restrain the proliferation of C. rodentium during the late phase of infection, leading to ~40% mortality." (PMID 39379604, 2024). "As mice lacking IL22 are unable to clear C. rodentium and succumb to the infection, the authors considered if a lack of IL22 production by this subset of TH17 cells underpinned the phenotype of C. rodentium GclcfloxCD4Cre mice." (PMID 39544255, 2024). "We found that infection of both populations of recruited lymphocytes was minimal, but that recruited γδ T cells, but not other lymphocytes, also produced IL-22." (PMID 38543790, 2024). "IL-22 and TIMP1 expression was found to be similar at all time-points point infection." (PMID 37218575, 2023). "To determine if the lack of IL-22 stimulation impacts the fate of alveolar BC following PR8 infection, we co-stained pod regions observed in parenchymal tissue of PR8-infected WT and IL-22 LOF mice for BC and IS markers." (PMID 37726288, 2023). "To further explore roles for innate immune activation and IL-22 in the regulation of epithelial cells in the airways and alveoli of PR8-exposed mice, we used scRNAseq to define changes to immune cell populations elicited in response to infection." (PMID 37726288, 2023). "Finally, we detected equivalent levels of IL-2, IFN-y, TNF-α, IL-12, IL-17, IL-22, IL-23, TGF-β, and IL-10 in the lungs of anti-Gr1-treated and control mice during the chronic phase of infection." (PMID 36776848, 2023). "However, hBC observed within airway and alveolar regions of both IL-22 LOF and IL-22r cLOF mice at 14 days post-PR8 infection showed significantly reduced levels of Ki67 staining compared to their corresponding WT controls." (PMID 37726288, 2023). "In comparison, TH17 cells did not yet produce significant amounts of IL-22 at this early time point of infection." (PMID 37453568, 2023). "While the study reported infection with C. rodentium lacking EspO reduced IL-22 secretion by colonic explants and a subsequent reduction in antimicrobial peptides, no change in the frequency of IL-22 producing ILC3s or T cells was observed." (PMID 37483638, 2023). "In murine, not only C. rodentium infection but also DSS-induced inflammation, Ffar2 agonists or propionate differentially activate AKT or ERK signaling pathways, and then increase ILC3-derived IL-22 through the AKT and STAT3 axis to confer protection against infection." (PMID 37318214, 2023).
infection (continued). "Studies have shown that mice who lacking IL-17A and IL-17F developed spontaneous infection with Staphylococcus aureus, while IL-22-/- mice showed increased colonization of Staphylococcus aureus and decreased expression of antibacterial proteins by 10%." (PMID 37304260, 2023). "Non-T lymphoid CD3- subsets did not contribute to the IL-22-expressing lineage following PR8 infection." (PMID 37726288, 2023). "Interestingly, IL-22, similar to IFN-λ, is another member of the IL-10 cytokine family that functions at epithelial mucosal barriers in response to infection." (PMID 36379255, 2022). "The infection with HN878 is known to induce a different inflammatory pattern (e.g., strong production of IL-1β and type 1 IFN) and protective mechanisms (e.g., IL-17 and IL-22 production) compared to H37Rv." (PMID 35443177, 2022). "In contrast, IL-22 injection into Il-18−/− mice failed to promote mucin secretion, which is reminiscent of the results that IL-22 injection also failed to restore Paneth cell or IFNγ response in Il-18−/− mice during AIEC infection." (PMID 35169117, 2022). "In contrast, there was little cytokine production evident in Th17 cells in homeostasis, but a marked induction of IL22 and IL17, even at this early time point post infection before a primary adaptive response would have time to occur, suggestive of a recall response." (PMID 35845169, 2022). "Moreover, previous studies have found that IFN-α, IFN-β, IFN-γ, and IL-22 expression were negatively correlated with Clostridium cluster XI, Escherichia, and Shigella species post AIV infection." (PMID 36230299, 2022). "Although WT mice were highly resistant to systemic C. rodentium infection, mice lacking the IL-22-HPX axis succumbed to infection." (PMID 33440153, 2021). "Furthermore, the cohoused FIJI mice secreted significantly higher quantities of IL-17 and IL-22 compared to the single-housed FIJI mice and equivalent quantities to those produced by both GUAT groups 14 days post-infection." (PMID 34320343, 2021). "Although the experimental design of this transcriptomic study did not allow us to distinguish which cell types differentially express IFN-γ, IL-22 or iNOS, we determined that NK cells, and to a lesser extend γδ T cells, were the main source of IFN-γ production in response to Mb04-303 infection." (PMID 34335572, 2021). "At early time points, Fpr2-/- mice showed a significant decrease in CXCL1, CXCL2, IL-1β, CCL2, GM-CSF, IL-6, and CCL3 levels at 1 hour and 3 hours after infection, and an increase in IL-22 and IL-23, but there is no change in TNF-α, as compared with WT mice." (PMID 34899755, 2021). "In infected CS-exposed mice, higher levels of IFN-γ, IL-17 were detected compared to the controls whereas the levels of IL-22 were not induced by the infection in both unstimulated and HK NTHi stimulated lung cells (p<0.05)." (PMID 33784296, 2021). "Accordingly, mice lacking LTβ on ILC3s fail to produce IL-22 in response to the mucosal bacterial pathogen Citrobacter rodentium (C. rodentium) and succumb to infection." (PMID 34938670, 2021). "Prior to infection, DP T cells showed higher TNF-α, IL-10, MIP-1β, and IL-22 expression than traditional CD4 and CD8 T cells, suggesting that these cells may potentially perform a non-specific function in the pulmonary immune response." (PMID 34929014, 2021). "Studies on the role of IL-22 in the injured lung have been limited to infection models and no such published studies have examined its role in ALI or ARDS." (PMID 34597299, 2021). "Further investigation in mice revealed that in lethal infections, IL-22 does not have any impact on the outcome, but in sublethal infections it is important for limiting inflammation and initiating tissue repair." (PMID 32974217, 2020). "We also noted that colonic ILC3s, ILC1s, and NKs coexpressed T-bet and RORγT, the transcription factors that are necessary for IFN-γ and IL-22 expression, respectively, regardless of infection status." (PMID 32051277, 2020).
infection (continued). "The absence of IL-22 impaired the clearance of the yeasts in the lungs and promoted spreading to the spleen at the 14th day post-infection." (PMID 32517114, 2020). "Although microglia were infected by ZIKV, IL-22 did not contribute to this infection or cell activation, as evidenced by similar levels of viral loads and comparable gene expression of activation markers following IL-22 supplementation in vitro." (PMID 32843067, 2020). "Qiu and colleagues (2012) found that AHR-deficient ILCs lack the IL-23 receptor (IL-23R) and that AHR KO mice express IL-22 at reduced levels and, unlike wild-type mice, succumb to infection with C. rodentium." (PMID 32784381, 2020). "Although IL-22 exhibited a dispensable role for glial cell activation and infection in vitro, the lack of IL-22 resulted in decreased microglia activation in vivo." (PMID 32843067, 2020). "Therefore, Il22−/− mice were treated with LTB4 (50 ng) or vehicle one day before, and during infection with H. capsulatum, while survival was monitored for 28 days." (PMID 32517114, 2020). "Thus, we evaluated IL-17- and IL-22-producing CD4+ T cells at 6 h (for immediate early) and (24 h for early response) post-infection in the lungs of mice immunized with PBS versus Trivalent-FP." (PMID 32340134, 2020). "In addition to differences that exist at steady state, there is evidence linking IL-22 and FUT2 during infection." (PMID 32185141, 2020). "On the contrary, only 10% of IL-22-/- mice developed paralysis during the infection; neither seizure nor death was observed in the absence of IL-22." (PMID 32843067, 2020). "Subsequently, we sought to examine the influence of Ss infection on the systemic levels of Type-1 (IFN-γ, TNF-α, and IL-2), Type-17 (IL-17A and IL-22), Type-2 (IL-4, IL-5, and IL-13), regulatory (IL-10) and pro-inflammatory cytokines (IL-1α, IL-1β, IL-6, IL-12, and GM-CSF) in INF and UN individuals." (PMID 33042134, 2020). "Whilst the current study did not examine these particular components of the immune system, infection of the co-culture model in the presence of CM from PBMCs already primed by BCG showed no significant further increase in either IL17a or IL22." (PMID 33116165, 2020). "Before infection, the mRNA levels for ifn-γ, il-17, and il-22 were low and not different in D+ WT, D- WT, and D- Cyp KO mice." (PMID 30723466, 2019). "Treating D- Cyp KO mice with IL-22 Fc protected the mice from early lethality (100% survival to d14 post infection) as compared to D- Cyp KO isotype treated mice (data not shown)." (PMID 30723466, 2019). "appears to predominantly induce a Th1 response as IL-17 and IL-22 levels did not significantly change in a mouse model of infection." (PMID 30873151, 2019). "Wild-type C57Bl/6 mice and many immunocompetent strains show little or no mortality with CR infection; in striking contrast, interleukin-22 knockout (Il22-/-) mice display dramatically elevated morbidity and mortality rates during CR infection." (PMID 31251784, 2019). "A recent study demonstrates that CR infection triggers a strikingly elevated mortality in Il22-/- mice, but not wild-type C57Bl/6 animals." (PMID 31251784, 2019). "ChAT-GFP+ IL-22+ T-cell population appears to be persistent in the naïve colon and does not increase significantly during infection." (PMID 30973939, 2019). "We have shown that upon infection with whipworms, signalling by IL-10, but not IL-22 or IL-28, is crucial for the resistance to colonization by opportunistic pathogens, control of host inflammation, intestinal barrier maintenance and worm expulsion." (PMID 30640950, 2019). "In keeping with the proliferation data, Il-22 transcription and protein levels were strongly upregulated following infection with the POR1 and POR2 strains but remained close to baseline following infection with POR3." (PMID 31848276, 2019). "Based on research into IL-17 and IL-22 production and its importance in this disease implicates ILC3 may be responding to infection." (PMID 30873151, 2019).
infection (continued). "In contrast, the expression levels of TNF-α (P = 0.039), IL-22 (P = 0.033) and IL-6 (P = 0.016) in jejunal mucosa at 12 h and IL-22 (P = 0.030) expression in ileal mucosa at 72 h post infection, were markedly upregulated in nonspecific yolk powder group." (PMID 31286936, 2019). "We observed a significant reduction in IL-22-producing ILC3s in naïve Hic1Rorc mice and infection with C. rodentium failed to expand the small number of ILC3s in Hic1Rorc mice." (PMID 29470558, 2018). "Secondly, mice lacking cytokines of Th1 and Th17 origin (IL-12, IL-22 and IL-17) are more vulnerable to infection, indicating that these also have roles in controlling C. rodentium infection." (PMID 30252907, 2018). "In agreement with the transcriptomic data, several cytokines (e.g. IL-11 and IL-22) were found to increase upon infection, but no strong difference was observed between wildtype and ΔcnfY mutant-infected animals." (PMID 29390040, 2018). "Infection with Citrobacter rodentium triggers robust tissue damage repair responses, manifested by secretion of IL-22, in the absence of which mice succumbed to the infection." (PMID 30365535, 2018). "On the other hand, the expression of IL-21, IL-22, and IL-23 did not change significantly depending on the stage of infection." (PMID 29698503, 2018). "Correlating to Mtb loads, when BCG primed mice were boosted with LP-ESAT-6 subunit vaccine after infection with Mtb, there were higher levels of IFN-γ, IL-17A, and IL-22 and lower levels of IL-10 compared to BCG-vaccinated mice, demonstrating the increase in protective immunity." (PMID 30386336, 2018). "The mRNA levels of ileal Tnfα, Il-1β, Il-22, Il-10, Foxp3 and RegIIIγ were comparable between Tac and Jax mice regardless of infection status." (PMID 29789574, 2018). "The RH group had lower IL-22 levels than the ME49 group at day 3, 5, 7, and 9 post-infection." (PMID 30564216, 2018). "Our experiments demonstrated that IEC-specific MyD88 reconstitution did not affect IL-22 production from ILC3 upon infection, indicating that the enhanced expression of RegIIIγ is not exclusively dependent on ILC3 activation." (PMID 28520792, 2017). "However, at all periods of infection studied, a significant increase in the number of ILC3 and NRC IL-22 was observed in the lungs of IDO1−/− mice." (PMID 28791025, 2017). "At early stage of infection, PFOS prevents the expansion of C. rodentium by promoting the IL-22 production from the group 3 innate lymphoid cells (ILC3s) through activating aryl hydrocarbon receptor (Ahr), which is a key transcription factor known to regulate the development and function of ILC3s." (PMID 28701769, 2017). "This negative effect on IL-22 implicated MAPK signaling as one of the required pathways in ILC3s for IL-22 production, which means that B. anthracis may inhibit ILC3 function during infection, potentially aiding its bacterial dissemination." (PMID 29059238, 2017). "Notably, despite enhanced IL-22 level at both early and late stage of infection in PFOS treated mice, the expression of anti-microbial peptides was higher only at early phase of infection." (PMID 28701769, 2017). "In both early and late stages of infection (6 and 15 months post infection), IL-22 transcription was significantly lower when compared with non-infected healthy control dogs." (PMID 27094260, 2017). "In individuals with inflammation in the absence of infection the IFNG/IL22 and NK cell response was reduced, however, pro-inflammatory, growth and matrix factors remained upregulated and mucins were downregulated." (PMID 28966918, 2017). "Il22 mRNA was induced in the spleen and in the heart on day 14 post infection, whereas it was not detectable in the liver during the infection." (PMID 27650379, 2016). "Accordingly, parasite burdens in spleens, livers and hearts were decreased at day 28 post infection in the absence of IL-22." (PMID 27650379, 2016).